P2RX1 (purinergic receptor P2X 1)
Description:
ATP-gated nonselective transmembrane cation channel permeable to potassium, sodium and with relatively high calcium permeability. Furthermore, CTP functions as a weak affinity agonist for P2RX1. Plays a role a role in urogenital, immune and cardiovascular function (By similarity). Specifically, plays an important role in neurogenic contraction of smooth muscle of the vas deferens, and therefore is essential for normal male reproductive function (By similarity). In addition, contributes to smooth muscle contractions of the urinary bladder (By similarity). On platelets, contributes to platelet activation and aggregation and thereby, also to thrombosis (By similarity). On neutrophils, it is involved in chemotaxis and in mitigating the activation of circulating cells.
Synonyms: P2X1
Tractability: Small molecule: a structure with a bound ligand is known; a high-quality ligand is known; it belongs to a druggable protein family. Antibody: UniProt places it where antibodies can reach, with high confidence; its Gene Ontology location is reachable by antibodies, with high confidence; UniProt predicts a signal peptide or a membrane-spanning region. PROTAC: its protein half-life has been measured; a small molecule that binds it is known.
Target class: Ligand-gated ion channel; P2X receptor; Ion channel
Safety:
Unwanted effects reported when the protein is acted on. In parentheses: how it was acted on, where the effect was seen, and who reports it.
decreased convulsions (inhibition, acute dosing; nervous system, renal, immune; source: Lynch et al. (2017))
decreased inflammation (inhibition, acute dosing; nervous system, renal, immune; source: Lynch et al. (2017))
decreased pain (inhibition, acute dosing; nervous system, renal, immune; source: Lynch et al. (2017))
hemolysis (activation, acute dosing; nervous system, renal, immune; source: Lynch et al. (2017))
increased pain (activation, acute dosing; nervous system, renal, immune; source: Lynch et al. (2017))
increased urinary sodium excretion (activation, acute dosing; nervous system, renal, immune; source: Lynch et al. (2017))
increased urine excretion (activation, acute dosing; nervous system, renal, immune; source: Lynch et al. (2017))
neurodegeneration (activation, chronic dosing; nervous system, renal, immune; source: Lynch et al. (2017))
Gene: Protein-coding gene on chromosome 17 (3,896,592 to 3,916,500, reverse strand). Ensembl gene ENSG00000108405.
Subcellular location: Cell membrane
Subcellular location (Human Protein Atlas): Endoplasmic reticulum
Pathways (Reactome):
Hemostasis: Elevation of cytosolic Ca2+ levels; Platelet homeostasis
Immune System: Neutrophil degranulation
Gene Ontology:
Molecular function: extracellularly ATP-gated monoatomic cation channel activity; ligand-gated calcium channel activity; monoatomic cation channel activity; protein binding; purinergic nucleotide receptor activity; ATP binding; identical protein binding; monoatomic ion channel activity; nucleotide binding; protein-containing complex binding; suramin binding
Biological process: monoatomic ion transport; calcium ion transmembrane transport; signal transduction; calcium-mediated signaling; excitatory postsynaptic potential; monoatomic cation transmembrane transport; monoatomic ion transmembrane transport; neuronal action potential; positive regulation of calcium ion import across plasma membrane; purinergic nucleotide receptor signaling pathway; regulation of blood pressure; regulation of presynaptic cytosolic calcium ion concentration; regulation of synaptic vesicle exocytosis; response to ATP; synaptic transmission, glutamatergic
Cellular component: membrane raft; plasma membrane; secretory granule membrane; specific granule membrane; external side of plasma membrane; glutamatergic synapse; membrane; postsynaptic membrane; presynaptic active zone membrane; protein-containing complex
Genetic constraint (gnomAD): Loss-of-function variants: 42 observed, 50.25 expected, observed/expected ratio (o/e) 0.84, 90% interval 0.65 to 1.08. The upper end of that interval is the gene's LOEUF score, 1.08, which puts it in group 4 of 6, group 1 being the genes least tolerant of losing a copy. Missense variants: 443 observed, 545.78 expected, observed/expected ratio (o/e) 0.81, 90% interval 0.75 to 0.88. Synonymous variants: 199 observed, 209.35 expected, observed/expected ratio (o/e) 0.95, 90% interval 0.85 to 1.07.
Homologues: Orthologues: chimpanzee P2RX1 (99% identical), macaque P2RX1 (98% identical), dog P2RX1 (91% identical), guinea pig P2RX1 (91% identical), mouse P2rx1 (89% identical), rabbit P2RX1 (89% identical), rat P2rx1 (89% identical), pig P2RX1 (84% identical), tropical clawed frog p2rx1 (62% identical), zebrafish p2rx1 (52% identical). Paralogues in human: P2RX4 (47% identical), P2RX3 (42% identical), P2RX6 (40% identical), P2RX7 (40% identical), P2RX5 (39% identical), P2RX2 (37% identical).
Diseases named in the same sentence as P2RX1 in open-access papers:
P2RX1 is named in the same sentence as 69 diseases in open-access papers, as found by Europe PMC text mining. Sharing a sentence is not in itself a finding about the gene and the disease. The quoted sentences say what the papers report.
Sepsis (7 papers, 2017 to 2025). Sepsis is defined as life-threatening organ dysfunction caused by a dysregulated host response to infection. "RT-PCR analysis of PBMCs from 29 sepsis patients and 11 healthy controls revealed significant differential expression of CFD and P2RX1 (p < 0.05), with greater variability observed in the sepsis group." (PMID 41285832, 2025). "In addition, CD59, SERPINB2, CFD, and P2RX1 can be potential biomarkers for sepsis diagnosis." (PMID 41285832, 2025).
lung carcinoma (6 papers, 2020 to 2025). "Previous studies have shown that P2RX1 is associated with the carcinogenesis, and prognosis of pancreatic cancer and lung cancer." (PMID 35585027, 2022). "In lung cancer research, low P2RX1 expression was found to be associated with poor prognosis." (PMID 35585027, 2022). "In lung cancer, the expression level of the P2RX1 receptor is closely related to the prognosis of patients; patients with low expression of P2RX1 often have a poor prognosis." (PMID 41502525, 2025). "In many other tumor types, P2RX1 has also been shown to have prognostic value, such as lung cancer and pancreatic cancer, which is consistent with the findings in this study." (PMID 35585027, 2022). "created a novel Lung cancer prediction model that integrates 5 PyMGs, including P2RX1, P2RX7, P2RY12, P2RY13, and P2RY14, which might be utilized to predict prognosis in Lung cancerpatients." (PMID 37664033, 2023). "However, P2RX1, P2RX7, P2RY12, P2RY13, and P2RY14 were relatively downregulated in lung cancer tissues and were associated with a favourable prognosis." (PMID 33501930, 2021). "However, purinergic receptors P2RX1, P2RX7, P2RY12, P2RY13, and P2RY14 were relatively downregulated in lung cancer tissues and were associated with favorable prognosis." (PMID 32638267, 2020). "We also showed that contrast with the unfavorable prognosis of pyrimidine metabolic rate–limiting enzymes, purinergic receptors P2RX1, P2RX2, P2RX7, P2RY12, P2RY13, and P2RY14 were favorable prognostic markers in patients with lung cancer." (PMID 32638267, 2020). "Next, we determined the expression levels of P2X sub-families P2RX1–7 and P2Y receptors P2RY1, P2RY2, P2RY4, P2RY5 (LPAR6), P2RY6, P2RY7 (LTB4R), P2RY8, P2RY9 (LPAR4), P2RY10–14 in normal lung tissues and lung cancer tissues." (PMID 32638267, 2020). "However, the exact mechanisms by which PSMC1, P2RX1, and GJB3 are involved in the progression of lung cancer have not yet been reported in the literature and warrant further exploration." (PMID 36091041, 2022).
colitis (5 papers, 2015 to 2023). Inflammation of the colon. "Together, these results suggest that P2RX1 antagonist can facilitate the efficiency of anti-TNF-α therapy in mouse colitis, and the mechanism is associated with decreased inflammatory cytokine and neutrophil infiltration." (PMID 34354708, 2021). "P2RX1 is linked to the modulation of microbiota and the alleviation of inflammation in colitis." (PMID 37298680, 2023). "Next, flow cytometry was performed to determine the involvement of P2RX1 in neutrophil and macrophage infiltration in colitis." (PMID 34354708, 2021). "To explore the potential link between P2RX1 and intestinal microbiota in colitis, we performed 16S rDNA sequencing." (PMID 34354708, 2021). "Using P2RX1 knockout mice, we observed that P2RX1 ablation significantly relieved dextran sulfate sodium (DSS)-induced mouse colitis." (PMID 34354708, 2021). "RNA sequencing results of colon tissues showed that genetic knockout of P2RX1 suppressed the inflammation responses in DSS-induced mice colitis." (PMID 34354708, 2021). "Together, these results suggest that P2RX1 ablation is sufficient to suppress DSS-induced mouse colitis." (PMID 34354708, 2021). "Genetic ablation of P2RX1 relieved dextran sulfate sodium (DSS)-induced mice colitis." (PMID 34354708, 2021). "Finally, we found that a specific P2RX1 inhibitor succeeded to improve the therapeutic efficiency of anti-TNF-α therapy in DSS-induced mice colitis." (PMID 34354708, 2021). "It suggested that host-expressed P2RX1 might contribute to shaping the plasticity of intestinal microbiota in colitis." (PMID 34354708, 2021). "Given the important role of P2RX1 in thrombosis, a recent study showed that P2RX1 deficiency inhibited peripheral platelet activation and caused subsequent coagulation dysfunction in high DSS dosage-induced severe colitis (5% for 7 days)." (PMID 34354708, 2021). "In addition, combination of a P2RX1 inhibitor facilitated the therapeutic efficiency of TNF-α monoclonal antibody (mAb) in mice colitis." (PMID 34354708, 2021). "Then, purinergic receptor P2RX1 was genetically ablated in the background of C57BL/6 mice, and dextran sulfate sodium (DSS) was used to induce mice colitis." (PMID 34354708, 2021).
pancreatic cancer (4 papers, 2020 to 2025). "It has been documented that the low P2RX1 expression of immune cells contributes to a condition of tumor immunosuppression, thereby promoting liver metastasis of pancreatic cancer." (PMID 35585027, 2022). "A previous study showed that the accumulation of immunosuppressive P2RX1-negative neutrophil subsets causes metastatic pancreatic cancer to evade antitumor immunity." (PMID 35585027, 2022). "For example, in studying pancreatic cancer liver metastasis, it was found that P2RX1-negative neutrophil subpopulations accumulated significantly in the tumor microenvironment." (PMID 41502525, 2025).
asthma (3 papers, 2021 to 2025). "Taken together, these data suggest that of the P2X receptors, P2RX1, P2RX4, and P2RX7 are likely to be the most credible targets for respiratory diseases such as asthma." (PMID 35386996, 2021).
breast carcinoma (3 papers, 2020 to 2022). "Then we validated that P2RX1 was differentially expressed in two human breast cancer cell lines compared to normal human mammary epithelial cell line." (PMID 35585027, 2022). "Although P2RX1 is highly expressed in para-cancerous tissues, this study found that normal human mammary epithelial cells express lower P2RX1, compared to human breast cancer cells." (PMID 35585027, 2022). "RT-qPCR demonstrated that the expression of P2RX1 in normal human mammary epithelial cells (MCF 10A) was significantly downregulated, compared with that in human breast cancer cells (MDA-MB-231, MCF-7)." (PMID 35585027, 2022).
gastric cancer (3 papers, 2023 to 2025). A primary or metastatic malignant neoplasm involving the stomach. "In gastric cancer research, P2RX1 expression in neutrophils is linked to the JAK/STAT signaling pathway." (PMID 40625358, 2025). "The overexpression of P2RX1 in gastric cancer neutrophils increases the apoptosis of cancer cells while inhibiting the migration, invasion, and viability of cells." (PMID 41502525, 2025). "Overexpression of P2RX1 boosts neutrophil survival via this pathway, reducing gastric cancer cell migration, invasion, and proliferation while increasing apoptosis." (PMID 40625358, 2025).
acute lymphoblastic leukemia (2 papers, 2023 to 2025). Leukemia with an acute onset, characterized by the presence of lymphoblasts in the bone marrow and the peripheral blood. "In the lymphoblastic leukemia cell line Jurkat, ATP-induced tension generation and autocrine stimulation of P2RX1 and P2X7 have been observed to increase calcium influx and mitochondrial metabolism, thereby promoting cell proliferation." (PMID 41458092, 2025).
depression (2 papers, 2013 to 2021). "Both the QIDS and HRSD displayed positive associations for depression and gene expression for ion channels P2RX1 and P2RY1, further strengthening the possible relationship of ion channels and depression." (PMID 24143878, 2013). "With the DD sample, greater depression severity (whether defined by QIDS or by HRSD scores) was associated with higher expression of ion channels P2RX1 and P2RY1." (PMID 24143878, 2013). "Depression severity was related to increased IL-10, P2RY1, P2RX1, and TRPV4 expression." (PMID 24143878, 2013). "Finally, two additional ion channel genes, P2RX1 and TRPV4, as well as two of the genes from our primary analysis, IL-10 and P2RY1, were related to depression severity as assessed by the QIDS and/or HRSD." (PMID 24143878, 2013). "Of the 9 ion channel receptors that we examined, P2RX7, TRPV1, and P2RY1 were upregulated in female patients during a depressive episode, and P2RY1 expression was positively related to depression severity along with 2 other ion channel receptors, TRPV4 and P2RX1." (PMID 24143878, 2013).
HIV-1 infection (2 papers, 2015 to 2020). The type species of lentivirus and the etiologic agent of acquired immunodeficiency syndrome (AIDS). "P2RX7 and P2YR antagonists have been shown to inhibit HIV-1 infection at potencies similar to those of P2RX1 antagonists, but these compounds do not appear to impact virus-cell membrane fusion." (PMID 32155980, 2020).
male infertility (2 papers, 2021). The inability of the male to effect fertilization of an ovum after a specified period of unprotected intercourse. "Published reports have identified the roles of P2RX1 in male infertility, vasoconstriction, and thrombosis." (PMID 34354708, 2021).
bladder cancer (1 paper, 2024). "The P2RX1 gene’s high expression increases the risk of distant metastasis of bladder cancer cells." (PMID 38180750, 2024).
breast tumor (1 paper, 2022). "To evaluate whether P2RX1 is highly expressed in mammary epithelial cells, we examined the matched breast tumor/normal pairs by RT-qPCR and Western blot." (PMID 35585027, 2022).
endometriosis (1 paper, 2025). The growth of functional endometrial tissue in anatomic sites outside the uterine body. "Furthermore, the identification of upregulated genes, such as SIRT1, SBDS, SRF, SPN, P2RX1, TEAD3, and SLITRK3, alongside downregulated genes, including KIF22, KIF25, GAS2L2, and HINT3, highlights a broad transcriptional reprogramming within endometriosis-affected tissues." (PMID 41516028, 2025).
injury (1 paper, 2023). Damage inflicted on the body as the direct or indirect result of an external force, with or without disruption of structural continuity. "It first demonstrated the protective effects of P2rx1 deficiency on acetaminophen-induced liver injury (AILI)." (PMID 37046119, 2023).
liver disorder (1 paper, 2023). A disease involving the liver. "P2RX1 is closely associated with human liver disorders, however, its pivotal nature and its translational application are yet unclear, calling for extensive exploration." (PMID 37046119, 2023).
multiple sclerosis (1 paper, 2020). A progressive autoimmune disorder affecting the central nervous system resulting in demyelination. "P2X purinoceptor 1, encoded by P2rx1, potentiates neurite outgrowth, while mutations in sodium voltage-gated channel alpha subunit 10, encoded by Scn10a, has been implicated in neurological disorders like multiple sclerosis and Pitt-Hopkins." (PMID 32582210, 2020).
pulmonary arterial hypertension (1 paper, 2019). Pulmonary arterial hypertension (PAH) is a group of diseases characterized by mean pulmonary artery pressure >20 mmHg and elevated pulmonary arterial resistance leading to right heart failure. "Stimulation of these cells induces vasoconstriction in a P2RX1-dependent manner, resulting in pulmonary arterial hypertension, which is in part responsible for edema formation." (PMID 30914724, 2019).
renal papillary cell carcinoma (1 paper, 2022). "The potential lncRNA of hsa-let-7d-5p and hsa-let-7e-5p/P2RX1 axis was STAG3L5P-PVRIG2P-PILRB, which has been reported to be up-regulated in renal papillary cell carcinoma and may be associated with poor prognosis." (PMID 35585027, 2022).